EGFR (epidermal growth factor receptor)
Diseases named in the same sentence as EGFR in open-access papers (continued):
Sharing a sentence is not in itself a finding about the gene and the disease.
hepatocellular carcinoma (continued). "In hepatocellular carcinoma (HCC), GalNAcT1 is frequently upregulated, which facilitates HCC cell migration and invasion by increasing the O-glycan addition to EGFR." (PMID 27322213, 2016). "MiR-302b was frequently down-regulated, whereas EGFR was up-regulated in human hepatocellular carcinoma (HCC)." (PMID 26646588, 2016). "Therefore, interventions to reduce activated HSCs by targeting EGFR signaling pathway may be an attractive therapeutic strategy in both hepatic fibrosis and hepatocellular carcinoma." (PMID 26550019, 2015). "Hepatoma cell lines that were classified as epithelial due to their E-cadherin expression were sensitive to EGFR inhibitors, whereas hepatoma cell lines classified as mesenchymal (vimentin-positive) were resistant to EGFR inhibitors and displayed increased Akt and STAT3 phosphorylation." (PMID 26729094, 2015). "In hepatocellular carcinoma, cisplatin and 5-fluorouracil treatment enhance SPINK1 transcriptional activity and drive chemoresistance via the EGFR-ERK-CDK4/6-E2F2 axis." (PMID 40904507, 2025). "For hepatocellular carcinoma (HCC), silibinin induces apoptosis by downregulating TGFα-EGFR autocrine loops and inhibiting survival pathways." (PMID 40650040, 2025). "Studies on in vitro models of hepatoma cells have revealed that L-theanine can significantly suppress the Met/EGFR/VEGFR-Akt/NF-κB pathway, thereby inhibiting the growth of hepatoma cells." (PMID 41228568, 2025). "Acquired lenvatinib resistance in hepatocellular carcinoma was driven by an EGFR/STAT3 axis, where STAT3 directly bound the ABCB1 promoter to upregulate P-gp and enhance drug efflux, and inhibiting either EGFR or STAT3 restored drug sensitivity." (PMID 41373605, 2025). "To explore the key targets and signaling pathways of Ansofaxine hydrochloride for inhibiting hepatocellular carcinoma, we first dock SRC, GRB2, PIK3R1, AKT1, and EGFR, which are in the front of the core genes." (PMID 40809022, 2025). "In hepatocellular carcinoma cells, ADAM17 plays a role in hypoxia-induced drug resistance by activating the EGFR/PI3K/Akt pathway." (PMID 39346916, 2024). "In hepatocellular carcinoma (HCC), YTHDF2 has a dual role: it increases the stemness and tumor growth of liver cancer stem cells (LCSCs) by increasing the translation of OCT4, but it also inhibits the proliferation and growth of HCC cells by decreasing the stability of EGFR." (PMID 38351531, 2024). "What’s more, GOLM1 also acts as a positive regulator of Programmed Cell Death Ligand 1 (PD-L1) expression via the EGFR/Signal Transducer and Activator Of Transcription 3 (STAT3) signaling pathway in the human hepatocellular carcinoma." (PMID 39190284, 2024). "In hepatocellular carcinoma, METTL1/WDR4-mediated m7G tRNA modification significantly promotes the translation of cyclin A2, EGFR, and VEGFA, promoting the spread and metastasis of hepatocellular carcinoma cells." (PMID 39019857, 2024). "This involves direct interaction with the 3′-UTR of ABCB1 and suppression of the EGFR-related phosphorylation of the ERK1/2 pathway, ultimately giving rise to increased sensitivity of hepatoma cells to doxorubicin." (PMID 39679367, 2024). "According to the previous research, GOLM1 can move from the trans‐Golgi network into the cytosol, where it can affect the cell surfaces recycling of EGFR/RTK, which is known to be essential for the development of hepatocellular carcinoma." (PMID 39470578, 2024). "CAR-T cells targeting GPC3 and EGFR (CARgpc3-egfr) have been developed and demonstrated comparable proliferative capacity and cytotoxicity to CARgpc3 T cells against GPC3 + EGFR+ hepatocellular carcinoma (HCC) in vitro." (PMID 38727261, 2024). "In this review, our aim is to provide an overview of the tumor-promoting effects exerted by the PI3K/AKT/mTOR signaling pathway in hepatocellular carcinoma (HCC), which is primarily triggered by the epidermal growth factor receptor (EGFR)." (PMID 37631344, 2023).
hepatocellular carcinoma (continued). "In this study, we characterized the functions of the late host entry factors: epidermal growth factor receptor (EGFR), claudin-1 (CLDN1), and occludin (OCLN) during HCV entry into polarized hepatoma spheroids." (PMID 38157366, 2023). "It possesses the ability to inhibit various targets, including epidermal growth factor receptor (EGFR), tyrosine kinase expressed in hepatocellular carcinoma (TEC), bone marrow kinase on chromosome X (BMX), and others." (PMID 38138527, 2023). "As EGFR activation is required for productive HCV entry and ADAMs can shed EGF, we asked if ADAM10 also transactivates EGFR in human hepatoma cells." (PMID 37967063, 2023). "In hepatocellular carcinoma, the METTL1/WDR4 complex promoted the translation of EGFR pathway genes via modulating m7G tRNA modification, which decreased the tumor’s susceptibility to Lenvatinib." (PMID 37710294, 2023). "Moreover, lnc-EGFR has also been shown to stimulate Treg differentiation, inhibit cytotoxic T lymphocyte activity, and induce hepatocellular carcinoma (HCC) growth." (PMID 37987366, 2023). "TsIIA inhibited the proliferation of hepatoma cell line SMMC-7721 and induced apoptosis in a concentration dependent manner, and down regulated the expression of EGF and EGFR." (PMID 36798821, 2023). "In hepatocellular carcinoma, female subjects were enriched with PPAR pathway, whereas males with PI3K, PI3K/AKT, FGFR, EGFR, and IL-2 signaling pathway." (PMID 36964522, 2023). "Combined EGFR and FGFR inhibition resulted in meaningful clinical responses in patients with advanced hepatocellular carcinoma." (PMID 35487914, 2022). "It is necessary to elucidate the target of CDCA as a target drug carrier for hepatocellular carcinoma, and this paper verified that CDCA is enhancing the therapeutic effect of sorafenib on hepatocellular carcinoma through EGFR/Stat3 pathway." (PMID 35252007, 2022). "For hepatocellular carcinoma, PLAGL2 weakens the effect of erlotinib, an anti-EGFR drug, through the EGFR-HIF-1/2α signaling pathway." (PMID 35565203, 2022). "In hepatocellular carcinoma, YTHDF2 directly binds to the m6A modification site of the 3′‐UTR of EGFR to promote the degradation of EGFR mRNA." (PMID 34647424, 2022). "And through the EGFR and VEGF pathway inhibited the cell proliferation, tumor micro-vessel production and metastasis of HCC, regulated autophagy and induced apoptosis of hepatoma cells." (PMID 35907976, 2022). "In esophageal squamous cell carcinoma and hepatocellular carcinoma, RNF128 promotes malignant tumor behavior through activation of the EGFR/ERK signaling pathway." (PMID 36644633, 2022). "In hepatocellular carcinoma and esophageal carcinoma, high expression of RNF128 promotes malignant behaviors in cancer cells through activation of the EGFR/ERK signaling pathway." (PMID 36644633, 2022). "In conclusion, we confirmed that CDCA enhances the inhibitory effect of sorafenib on hepatocellular carcinoma cells by in vivo and in vitro experiments, which relies on the binding of CDCA to EGFR." (PMID 35252007, 2022). "The latest studies found that S. officinalis exerted its therapeutic effects on hepatocellular carcinoma through interfering in cancer cell proliferation and survival via the EGFR/MAPK and EGFR/PI3K/AKT/NFκB signaling pathways." (PMID 35646655, 2022). "The activation of epidermal growth factor receptor (EGFR) could limit the efficacy of lenvatinib in hepatocellular carcinoma (HCC)." (PMID 36362068, 2022). "Specifically, it was found that GOLM1 recycles the EGFR and RTK membrane proteins resulting in Akt activation with commensurate oncogenic activity and metastatic progression in hepatocellular carcinoma." (PMID 34680291, 2021). "After up regulating the expression of mir-107 in hepatoma cell lines Huh7 and HepG2, the mir-107 bound to the 3‘-UTR region of the CPEB3 transcript, and resulted in an increased expression of EGFR and phosphorylated Akt and decreased expression of p21." (PMID 34879089, 2021).
hepatocellular carcinoma (continued). "It was shown that G144AXXXG148A mutation strongly diminished the interaction between NTCP and EGFR, finally leading to decreased preS1-peptide binding and HBV/HDV infection rates in NTCP-transfected hepatoma cells." (PMID 34239896, 2021). "In hepatocellular carcinoma (HCC), lnc-EGFR (epidermal growth factor receptor) was shown to promote differentiation of immunosuppressive Tregs offering a new therapeutic target for HCC." (PMID 34880875, 2021). "In hepatocellular carcinoma (HCC), Xmrk and EGFR signaling utilize STAT5 to regulate cell proliferation, and Xmrk may signal through PI3K and FasR to modulate apoptosis." (PMID 34067095, 2021). "This study reveals a novel cooperative role of Pgrmc1 in supporting the EGFR-mediated development of hepatocellular carcinoma, implying that pharmacological suppression of Pgrmc1 may be a useful strategy in HCC treatment." (PMID 34069911, 2021). "This is consistent with previous findings on m6A-binding protein YTHDF2 and modulating the location and stability of EGFR mRNA at its 3’UTR site, enhancing the degradation of the EGFR mRNA, and playing an anti-tumor role in hepatocellular carcinoma." (PMID 34084770, 2021). "For instance, lnc-EGFR can bind to and stabilize EGFR protein to activate AP-1/NFAT signaling axis, which stimulates Treg differentiation and inhibits the cytotoxicity of T cells to promote hepatocellular carcinoma development." (PMID 34760687, 2021). "For example, sublethal heat treatment increases EGFR m6A modification near the 5′UTR region and promotes its binding to YTHDF1, thereby enhancing the translation of EGFR mRNA and promoting hepatocellular carcinoma progression." (PMID 34026852, 2021). "In hepatocellular carcinoma cells, miR-374a promotes cell growth by targeting MIG-6 (ERRFI1), a negative regulator of EGFR signaling." (PMID 32674274, 2020). "These proteins, especially EGFR/HER2, are usually activated in many malignant tumors, including hepatocellular carcinoma (HCC) 2,3." (PMID 32398965, 2020). "While our studies indicate that KLF4 represses the expression of EGFR, Liu and colleagues have recently reported that KLF4 can stimulate EGFR gene expression in hepatocellular carcinoma cells." (PMID 32552913, 2020). "Overexpression of EGFR is frequently observed in hepatocellular carcinoma (HCC) and EGFR activation has been proven to be a potential determinant of primary resistance of HCC cells to sorafenib." (PMID 32190291, 2020). "In our previous study, we found 13 missense mutations in EGFR exon 19–23 from hepatocellular carcinoma (HCC) tissues, but the functions of these mutations have not been determined." (PMID 32190291, 2020). "We previously reported direct interaction between EGFR and CD133 in PDAC and hepatic carcinoma cells, where CD133 activates EGFR signaling." (PMID 30467381, 2019). "The epidermal growth factor receptor (EGFR) pathway and Hippo signaling play an important role in the carcinogenesis of hepatocellular carcinoma (HCC)." (PMID 29449645, 2018). "Regarding EGFR-TKI treatment, 1 LCV case during gefitinib treatment for adenoid cystic carcinoma of the maxilla and 2 LCV cases during erlotinib treatment for hepatocellular carcinoma were reported." (PMID 29732013, 2018). "It was shown that EGFR cooperated with integrin β4 (ITGB4) to promote anchorage-independent growth and metastasis of hepatocellular carcinoma." (PMID 30479571, 2018). "In the present study, several oncogenic RTKs, including EGFR, c-Met, HER3, and c-Kit, were found to be co-activated in HCC in the patient-derived hepatoma cells, HCC413." (PMID 30577605, 2018). "Our previous studies have shown that the activity of EGFR can be modified by GALNT1 and GALNT2 in hepatocellular carcinoma and by GALNT2 in oral squamous cell carcinoma." (PMID 28388560, 2017). "In cervical cancer and hepatocellular carcinoma, YAP1 can activate EGFR signaling by upregulating the expression of TGF-α or AREG." (PMID 29228705, 2017).
hepatocellular carcinoma (continued). "Our previous studies showed that GALNT2 modulated EGFR activity and suppressed EGF-induced proliferation, migration, and invasion in hepatocellular carcinoma cells." (PMID 26848976, 2016). "In human hepatoma-derived cells, transfection experiments using expression vectors of HBV x demonstrated that the x-gene product is capable of inducing EGFR overexpression." (PMID 26729094, 2015). "We recently showed that EGFR is decorated with mucin-type O-glycans, and the O-glycans and activity of EGFR can be modified by N-acetylgalactosaminyltransferase 2 (GALNT2) in hepatocellular carcinoma." (PMID 25003232, 2014). "In hepatocellular carcinoma (HCC), different signaling pathways are de-regulated, and among them, the expression of the epidermal growth factor receptor (EGFR)." (PMID 24886097, 2014). "This could be related to differences between (transformed) hepatoma cell lines and primary hepatocytes with regard to gene expression patterns, signaling cascades, GPCRs expression patterns and/or the ability of Gαi proteins to interact with the effector receptors such as EGFR." (PMID 22900098, 2012). "The current study aimed to investigate the expression levels of c-erb-B2, EGFR, PTEN, mTOR, PI3K, p27, and ERCC1 in hepatocellular carcinoma (HCC) and their correlation with other clinicopathologic features." (PMID 23162604, 2012). "We have reported that the selective epidermal growth factor receptor (EGFR) tyrosine kinase inhibitor, gefitinib (‘Iressa’, ZD1839), suppressed intrahepatic metastasis of hepatocellular carcinoma CBO140C12 cells." (PMID 15841081, 2005). "Examples include targeting EGFR and c-Met in NSCLC or GPC3 and MUC13 in hepatocellular carcinoma." (PMID 41348261, 2025). "Moreover, the activation of the proliferation and migration of hepatocellular carcinoma cells and LO2 cells by C. sinensis ESP are mediated by RAS/MAPK/ERK and PI3K/Akt signaling pathways and the activation of EGFR." (PMID 40732668, 2025). "MAOA inhibits the metastasis of hepatocellular carcinoma cells by suppressing the adrenergic system and activating the epidermal growth factor receptor (EGFR) signaling pathway, showing a negative correlation with hepatocellular carcinoma progression." (PMID 40225029, 2025). "Besides its intended BTK effects, ibrutinib also deactivates several off-targets, including epidermal growth factor receptor (EGFR), ErbB2, interleukin-2-inducible T cell kinase (ITK), and tyrosine kinase expressed in hepatocellular carcinoma (TEC)." (PMID 39518015, 2024). "Moreover, VPS35 knockdown weakened SNX5-induced EGFR degradation in hepatocellular carcinoma (HCC)." (PMID 37950040, 2024). "In hepatocellular carcinoma, NT5DC2 promotes tumor cell proliferation by stabilizing EGFR." (PMID 39684755, 2024). "Niu and colleagues showed that EGF-receptor-(EGFR)-mediated-signaling induced DKK1-expression in hepatocellular carcinoma cells, thereby creating a negative feedback loop on sensitized cells." (PMID 37532804, 2023). "Additionally, ZJP aqueous extract exhibited its prominent therapeutic effects on hepatocellular carcinoma (HCC) mainly via the regulation of cell proliferation and survival though the EGFR/MAPK, PI3K/NF-κB, and CCND1 signaling pathways." (PMID 36790599, 2023). "In addition, we also looked at the levels of p-EGFR, EGFR, p-STAT3, and total STAT3 protein expression, which are important signaling pathways involved in liver fibrosis and hepatocellular carcinoma." (PMID 37789318, 2023). "In addition, LINC01225 increased the protein level of EGFR by binding to EGFR, thereby activating the EGFR/MAPK signaling pathway and promoting the occurrence and metastasis of hepatocellular carcinoma." (PMID 38143380, 2023).
hepatocellular carcinoma (continued). "Most advance and successful examples include targeting BCR-ABL with imatinib in chronic myeloid leukemia, inhibiting EGFR with cetuximab in colorectal cancer, antagonizing BRAF with vemurafenib in melanoma, and inhibiting multiple tyrosine kinases with lenvatinib in hepatocellular carcinoma." (PMID 37427373, 2023). "lnc-EGFR was found to induce naive CD4+ T cell precursors to differentiate into Tregs, and the overexpressed lnc-EGFR increased the percentage of Tregs infiltrating in hepatocellular carcinoma and promoted the growth of the tumor." (PMID 37637063, 2023). "Finally, our molecular docking results against EGFR and BCL2 molecular targets support the potency of L. sativum’s major compounds against hepatocellular carcinoma." (PMID 34579396, 2021). "Additionally, GOLM1 is associated with surface membrane protein transport and recycling growth factor responsive receptor tyrosine kinase (RTK) and epidermal growth factor receptor (EGFR) proteins between the golgi and cell surface in hepatocellular carcinoma." (PMID 34680291, 2021). "The silencing of EGFR by miR-302b or siEGFR led to downregulation of proliferation-related proteins, such as AKT2, CCND1, and CDK2, and resulted in the inhibition of proliferation in hepatocellular carcinoma SMMC-7721 cells." (PMID 33688369, 2021). "In a study that investigating the mechanism of NEAT1 in hepatocellular carcinoma tissues, NEAT1 could regulate the expression of epidermal growth factor receptor (EGFR), thereby contributing to cancer cell proliferation." (PMID 34630395, 2021). "Abnormal expression of CPEB3 has been found in a variety of cancers, such as cervical cancer and human hepatocellular carcinoma; studies have found that miRNAs can directly target the CPEB3/EGFR axis to regulate tumor progression, but few studies are focusing on the nervous system." (PMID 34900520, 2021). "Furthermore, a heterodimer of EGFR and MET can phosphorylate Y907 of PARP1 in the nucleus of hepatocellular carcinoma and contribute to this resistance." (PMID 32093123, 2020). "In addition, we showed that ANGPTL4 regulates stemness in GBM through the EGFR/AKT/4E-BP1 cascade, which was supported by another study on hepatocellular carcinoma." (PMID 31717924, 2019). "However, that gefitinib inhibits FN-induced activation of ERK, p38, and Akt, as well as cell proliferation and invasion in hepatocellular carcinoma CBO140C12 cells, indicates that these FN responses are mediated by EGFR tyrosine kinase." (PMID 30187356, 2018). "The negative effect of GM3 was first demonstrated for EGFR signaling in a variety of cell lines including hepatoma, hepatocellular carcinoma and neuroblastoma cells." (PMID 27916834, 2016). "Activated miR-203a could suppress the hepatocellular carcinoma cells progression and induce the cell apoptosis by targeting HOXD3 through EGFR/AKT and ERK signaling pathway." (PMID 27244890, 2016). "Likewise, downregulation of GalNAcT2 in hepatocellular carcinoma (HCC) cells promoted cell growth, migration, and invasion in vitro and in vivo by modulating the O-glycan pattern on EGFR, resulting in EGFR activation by dimerization, and phosphorylation of downstream signaling proteins." (PMID 27322213, 2016). "Bim deletion polymorphism was significantly associated with the clinical efficacy of tyrosine kinase inhibitors in terms of response rate and disease control rate in EGFR-mutated NSCLC patients, but not in CML or hepatocellular carcinoma (HCC)." (PMID 26405162, 2015).